SLC11A1 (solute carrier family 11 member 1)
Diseases named in the same sentence as SLC11A1 in open-access papers (continued):
Sharing a sentence is not in itself a finding about the gene and the disease.
tumor (16 papers, 2017 to 2025). "We also observed that various immune activators and tumor progression-associated genes were enriched in high SLC11A1 groups, especially those related to cytokine signal transduction and PD-1 signal transduction." (PMID 36531992, 2022). "The high expression of CELF4, LPO, SLC11A1, and C7 in tumor tissues might be associated with poor prognosis, but they were not statistically significant (p-values of 0.09, 0.094, 0.06, and 0.21, respectively)." (PMID 37745305, 2023). "We hypothesize that high expression of SLC11A1 could reflect a tumor microenvironment tending to be “cold”, which also provides an explanation for the association of high SLC11A1 expression with poor prognosis." (PMID 36531992, 2022). "The results of immunochemistry showed that GBP2, HCLS1, P2RX7, and SLC11A1 were more highly expressed in the tumor group than in the normal group." (PMID 41007849, 2025). "For instance, anti-PD-1 therapy upregulates the solute carrier family 11 member 1 (SLC11A1) gene in the tumor microenvironment, promoting the differentiation of Th17 cells." (PMID 37680632, 2023). "qRT–PCR and immunohistochemistry (IHC) staining for SLC11A1 were used to evaluate SLC11A1 expression in tumor tissue samples and for further validation." (PMID 36531992, 2022). "Statistical analysis showed that high SLC11A1 expression related to older age, shorter survival time, higher tumor grade, GBM subtype, mesenchymal subtype, and wild type IDH, which further confirmed the findings from the TCGA analysis." (PMID 36531992, 2022). "As tumor progression and immune activation were both enhanced in the high SLC11A1 group, SLC11A1 expression possibly be related to the high PD-1 and CTLA4 expression." (PMID 36531992, 2022). "Notably, two of the 11 ICD-related genes that constitute the prognostic signature, SPP1 and SLC11A1, were exclusively expressed in macrophages within tumor samples." (PMID 40740776, 2025). "Additionally, SLC11A1 expression was correlated to age, IDH mutation status, tumor malignancy, 1p/19q codeletion and higher TMB." (PMID 36531992, 2022). "Similarly, the RT-qPCR results also validated that SLC11A1 expression was upregulated in tumor tissues." (PMID 36438826, 2022). "Thus, these consistent results further demonstrate that SLC11A1 plays a crucial role in the suppression of anti-tumor immunity and is a potential therapeutic target for CRC." (PMID 36438826, 2022). "M1 macrophage-related genes include IL-6, IL-8, CD80, PIM1, RTP4, and SLC11A1, and studies have shown that after metformin treatment, the expression of M1-related factors in tumor cells can be enhanced or weakened, thus affecting the prognosis of the tumor." (PMID 33193731, 2020). "Despite this, few studies have evaluated whether SLC11A1 contributes to tumor progression." (PMID 36531992, 2022). "There were substantial differences in CpG methylation in GBP2, SLC11A1, and HCLS1 between tumor and normal samples." (PMID 41007849, 2025). "By analyzing the correlation between five genes and tumor microenvironment, we found that SPP1, PRKCD, and SLC11A1 were highly positively correlated with macrophages." (PMID 34631695, 2021). "The mRNA levels of TEK, BMP1, AR, SLC11A1, SLC40A1, and F2RL1 were significantly downregulated in tumor cells compared with normal cells, and CX3CL1 and RNASE2 were upregulated in tumor cells." (PMID 35004689, 2021). "Highly relevant nodes in the modules, including STAT3, SLC11A1, and ITGAM, have been reported to promote tumor proliferation, angiogenesis, migration, and invasiveness." (PMID 32211315, 2020). "The phenomenon exhibits the phenomenon that immune activation was enriched in the high SLC11A1 subgroup while tumor progression was not suppressed." (PMID 36531992, 2022).
tumor (continued). "In the present study, we applied the ESTIMATE (Estimation of STromal and Immune cells in MAlignant Tumor tissues using Expression data) algorithm, hub gene analysis, and univariate COX regression and identified a TME-related factor in CRC, solute carrier family 11 member 1 (SLC11A1)." (PMID 36438826, 2022). "The results revealed that expression levels of SLCO4C1, POU4F1, DNASE1L2, WDR72, LPO, and C7 in tumor tissues were significantly higher than those in normal tissues, while the expression differences of SLC4A4, CELF4, and SLC11A1 were not statistically significant." (PMID 37745305, 2023).
endocrine disease (1 paper, 2023). "It has been established that variations in the SLC11A1 gene impact risk of developing infectious, inflammatory, and endocrine disorders." (PMID 37062790, 2023). "Our findings showed that SLC11A1 rs3731865 G/C is associated with an increased risk of T2DM in our population, while SLC11A1 rs3731864 G/A and rs17235416 + TGTG/−TGTG SNPs were correlated to decreased risk of developing this endocrine disease." (PMID 37062790, 2023). "Our findings showed a significant association between SLC11A1 polymorphisms and T2DM risk, where rs3731865 G/C markedly enhanced T2DM risk and both rs3731864 G/A and rs17235416 + TGTG/− TGTG variants significantly diminished the risk of this endocrine diseases under different genetic models." (PMID 37062790, 2023).
SLC11A1 also shares sentences with these, for which no sentence is quoted: glioblastoma (4 papers); Granuloma (3); Legionella infection (3); viral infection (3); acute myeloid leukemia (2); anaemia (2); autoimmune type 1 diabetes (2); chronic periodontitis (2); colon cancer (2); experimental autoimmune encephalomyelitis (2); gonococcal infection (2); Hypertension (2); iron deficiency (2); juvenile idiopathic arthritis (2); lung disease (2); malaria (2); multiple sclerosis (2); toxoplasmosis (2); adenocarcinoma (1); atherosclerosis (1); Burkholderia Infections (1); cardiac hypertrophy (1); co-infection (1); dementia (1); Diarrhea (1); disseminated candidiasis (1); endometrial carcinoma (1); enteropathy (1); gastrointestinal infection (1); immune deficiency (1).
A further 17 diseases each share a sentence with SLC11A1 in 1 paper.